CTLA4 (cytotoxic T-lymphocyte associated protein 4)
Diseases named in the same sentence as CTLA4 in open-access papers (continued):
Sharing a sentence is not in itself a finding about the gene and the disease.
metastatic melanoma (continued). "The researchers identified Treg cells as the source of this downregulation of CTLA-4 in metastatic melanoma patients." (PMID 38462628, 2024). "The discovery of ipilimumab (MDX-010), an IgG1 monoclonal antibody for CTLA-4, has greatly improved the treatment outcomes of metastatic melanoma, and its use in combination with PD-1 inhibitors has helped achieve a previously unimaginable increase in the OS." (PMID 39086722, 2024). "Subsets of patients with metastatic non–small cell lung cancer or metastatic melanoma also showed a combined effect of CTLA-4 blockade and RT." (PMID 38349740, 2024). "This is the first comparative study in patients with metastatic melanoma refractory to PD-1/CTLA-4 inhibition and showed significantly longer outcomes in cases treated with pembrolizumab/lenvatinib versus CC." (PMID 39435288, 2024). "Potential synergistic effect of cytotoxic T-lymphocyte-associated protein 4 (CTLA-4) blockade and hTERT vaccination was investigated in metastatic melanoma in a phase I/IIa clinical trial." (PMID 38384801, 2024). "The National Institute for Health and Care Excellence (NICE) approved ipilimumab (anti-CTLA4) for the treatment of metastatic melanoma in 2012 11, followed by pembrolizumab and nivolumab, which target the PD-1 axis." (PMID 38817862, 2024). "CTLA-4 blockade therapy was the first ICB approved by the FDA for the treatment of metastatic melanoma in 2011." (PMID 38398083, 2024). "CTLA-4 and PD-1 blocking antibodies have demonstrated synergistic effectiveness, particularly in the treatment of solid tumors such as metastatic melanoma." (PMID 39766080, 2024). "An exemplary approach is the combination of CTLA-4 and PD-1, which has demonstrated prolonged efficacy in metastatic melanoma compared to that achieved with individual therapies." (PMID 38791528, 2024). "Tremelimumab is a humanized anti-CTLA-4 IgG2 mAb with preliminary efficacy in metastatic melanoma as monotherapy." (PMID 39354625, 2024). "The first of these was the CTLA-4 inhibitor, Ipilimumab, approved in 2011 for metastatic malignant melanoma." (PMID 39273605, 2024). "The incidence of hypophysitis is 1–18% in metastatic melanoma patients treated with anti-CTLA4, and 0.5–1.5% for PD-1 inhibitors." (PMID 36769093, 2023). "In the case of an increased number of patients with metastatic melanoma who showed durable responses by immunotherapy, studies discovered synergism between immune checkpoint inhibitors which target CTLA-4, PD-1, and PDL-1." (PMID 37605149, 2023). "PD-1 inhibitors (nivolumab, pembrolizumab) and anti-CTLA-4 (CD152) (ipilimumab) are widely used in metastatic melanoma, and most immune-related adverse events are known." (PMID 37046831, 2023). "The clinical efficacy of anti-CTLA-4 antibodies was strongest in patients with advanced metastatic melanoma, with an ORR of 15%, and continued in some patients more than 10 years after treatment ended." (PMID 36810034, 2023). "qRT-PCR analysis showed that the expression of CTLA4 was significantly downregulated in PBMCs treated with MCM from metastatic melanoma cell lines (1205Lu, A375, and HS294T)." (PMID 37197667, 2023). "In contrast to the previous findings both low baseline butyrate and low baseline propionate (in serum) were correlated with longer PFS in metastatic melanoma patients treated with anti-CTLA-4 antibodies." (PMID 36769093, 2023). "The blockade of CTLA-4 and PD-1/PD-L1 with antibodies have been successfully used in metastatic melanoma." (PMID 36810034, 2023). "Subsequently, the SubMap analysis was conducted to compare the expression characteristics of FPTOS_score acquired from the TCGA and GEO databases with an open-access metastatic melanoma cohort who receiving anti-PD-1 or anti-CTLA-4 treatment." (PMID 37064095, 2023). "In this study, 26 patients with metastatic melanoma received anti-CTLA-4 and were closely observed for the development of colitis." (PMID 37298653, 2023).
metastatic melanoma (continued). "For instance, high blood butyrate and propionate levels were reported to be associated with resistance to CTLA-4 blockade in patients with metastatic melanoma, and oral administration of sodium butyrate diminished antitumor efficacy of anti-CTLA-4 in mice." (PMID 36880651, 2023). "This trend was similar in metastatic melanoma patients, while CTLA4 levels in CD45- cells were almost doubled compared to healthy donors." (PMID 37197667, 2023). "The inhibition of the programmed cell death protein 1 (PD-1) and cytotoxic T-lymphocyte-associated protein 4 (CTLA-4), as key immune checkpoint inhibitors, have been associated with a 6.5-year survival rate of 48% in patients with metastatic melanoma." (PMID 37297003, 2023). "Ipilimumab is a monoclonal antibody that works by blocking CTLA-4, mainly used for the treatment of metastatic melanoma." (PMID 37205307, 2023). "The discovery of checkpoint inhibition and the 2011 FDA approval of ipilimumab in metastatic malignant melanoma, a monoclonal antibody that blocks CTLA-4, marked the beginning of a new era in oncology." (PMID 36831607, 2023). "For metastatic melanoma, the most effective treatment at present is the application of immune checkpoint inhibitors, mainly including PD-1/PD-L1 and CTLA4 antibodies." (PMID 37427124, 2023). "Two commonly used immune checkpoint inhibitors (ICIs) utilized in the treatment of metastatic melanoma are nivolumab, a programmed death (PD-1) checkpoint inhibitor, and ipilimumab, a cytotoxic T-lymphocyte antigen (CTLA-4) checkpoint inhibitor." (PMID 38021498, 2023). "Immunotherapy with PD-1/PD-L1 and CTLA-4 inhibitors in the treatment of patients with metastatic malignant melanoma has greatly improved prognosis and survival." (PMID 37509655, 2023). "The humanized anti-CTLA-4 monoclonal antibody, Ipilimumab (Yervoy), is currently used to treat advanced metastatic melanoma.Furthermore, it’s important to note that CTLA-4, while expressed on Tregs, also has implications for conventional T cells." (PMID 37753092, 2023). "The same paper also reported that higher CTLA-4 protein levels in peripheral CD4+ and CD8+ T cells were associated with a better response to anti-PD1 therapy in metastatic melanoma." (PMID 37197667, 2023). "Recently, we provided evidence for CTLA4 methylation to serve as a predictive biomarker for anti-PD-1 and anti-CTLA-4 ICB in patients with metastatic melanoma and metastatic clear cell renal cell carcinoma." (PMID 37259155, 2023). "For example, in a cohort of metastatic melanoma patients treated with CTLA4 and PD-1 blockade, a deep immune analysis of tumor samples found that TNF was markedly upregulated after PD-1 treatment." (PMID 36865537, 2023). "In another study of patients with metastatic melanoma treated with a CTLA-4 and PD-1 blocking combination, Bacteroides dorei and B. vulgatus were found to be associated with irAEs in a reversed pattern." (PMID 37828613, 2023). "The CTLA4 expression levels in the Treg cell subset of metastatic melanoma patients were similar to those in the Tconv cell subset of metastatic melanoma patients and were even lower than those in the Tconv cells of healthy donors." (PMID 37197667, 2023). "For instance, ipilimumab was the first CTLA-4 inhibitor for treating metastatic melanoma approved by U.S. Food and Drug Administration (FDA) in 2011." (PMID 36765782, 2023). "While dual checkpoint inhibition with CTLA-4 and PD-1 inhibitors has become a well-established therapeutic option for metastatic melanoma with long-term OS results, this came at the expense of toxicity." (PMID 37484526, 2023). "ICI therapy has dramatically changed the treatment strategies for various cancer types since the approval of the CTLA-4 inhibitor for metastatic melanoma in 2011." (PMID 38136558, 2023).
metastatic melanoma (continued). "The current standard of care therapies for metastatic melanoma includes immune checkpoint inhibitors (ICIs), a novel class of therapeutics that inhibit cytotoxic T lymphocyte antigen-4 (CTLA-4) or the programmed death-1 receptor/ligand (PD-1/PD-L1)." (PMID 37509357, 2023). "In the treatment of metastatic melanoma, anti-CTLA-4 and anti-PD-1 checkpoint blockade increased 5-year overall survival from ~10% (prior to 2011) to ~50% (between 2011 and 2016)." (PMID 37182135, 2023). "Currently, there are four FDA-approved immunotherapy drugs for use in patients with advanced or metastatic melanoma: ipilimumab, an inhibitor of CTLA-4; pembrolizumab and nivolumab, both inhibitors of PD-1; and atezolizumab, an inhibitor of PD-L1." (PMID 37509357, 2023). "In fact, CTLA4 expression was downregulated by approximately 70% in Treg cell fractions of metastatic melanoma patients’ blood compared to healthy donors." (PMID 37197667, 2023). "Mechanistically, we provide evidence that the metastatic melanoma secretome induces post-transcriptional CTLA4 mRNA instability through the induction of miR-155." (PMID 37197667, 2023). "Previous therapy directed at LMD and/or metastatic melanoma is allowed, including IT therapy (washout 7 d), radiation (washout 7 d) and systemic biologic therapy (CTLA4 and/or PD, IL-2, interferon, washout 14 d)." (PMID 36997799, 2023). "Mechanistically, we found that secretomes from human metastatic melanoma cells downregulate CTLA4 mRNA at the post-transcriptional level through miR-155 while upregulating FOXP3 expression in human Treg cells." (PMID 37197667, 2023). "According to a pooled-analysis of anti-CTLA-4 Ipilimumab, more than 20% of treated patients with unresectable or metastatic melanoma experienced long-term survival for up to 10 years and suggested no cancer recurrence thereafter." (PMID 37711295, 2023). "Immunotherapies with immune checkpoint inhibitors, such as PD-1, PD-L1, and CTLA-4 inhibitors, have demonstrated promising survival advantages in metastatic melanoma, metastatic renal cancer, and non-small cell lung cancer for the past few years." (PMID 36707884, 2023). "Baseline MDSC and cytokine levels in patients with metastatic melanoma who received combinational anti-PD-1 and anti-CTLA-4 treatment." (PMID 36860876, 2023). "The use of anti-CTLA4 blocking antibody has the effect of increasing Th17 cells in patients with metastatic melanoma, which enhances immune toxicity." (PMID 36555549, 2022). "In 2011, the US Food and Drug Administration approved the humanized anti-CTLA4 antibody ipilimumab for the clinical treatment of metastatic melanoma." (PMID 36338658, 2022). "In another cohort of metastatic melanoma, patients with response to CTLA-4 therapy possessed a higher NRGscore." (PMID 35875102, 2022). "Only a few years after the clinical application of CTLA-4 blockade, PD-1 blockers achieved even significantly superior outcome for metastatic melanoma." (PMID 36698407, 2022). "CTLA-4 blockade used to be the most popular treatment for metastatic melanoma between 2010 and 2015; however, PD-1 blockade has taken over since 2015." (PMID 36698407, 2022). "In the case of advanced lung cancer or metastatic melanoma, a significant number (10%) of patients treated with CTLA-4 inhibitor incur damage to the pituitary gland." (PMID 36355837, 2022). "Incidentally, anti-PD-1 and anti-CTLA4 have achieved significant therapeutic effects in metastatic melanoma, which is consistent with our results." (PMID 36726781, 2022). "Treatment of metastatic melanoma patients with anti CTLA-4 antibody, resulted in significant increase in [18F]FLT signal in the spleen of some patients, at a median of two months after the start of therapy." (PMID 36700226, 2022). "Ipilimumab, a fully humanized IgG1 monoclonal antibody against CTLA4, is the first and only FDA‐approved CTLA4 inhibitor for metastatic melanoma." (PMID 35284650, 2022).
metastatic melanoma (continued). "Ipilimumab, a cytotoxic T-lymphocyte-associated protein-4 (CTLA-4) antibody, showed a durable response in metastatic melanoma patients with only four cycles of therapy." (PMID 36443704, 2022). "Following the approval of ipilimumab (anti-CTLA-4) by FDA to treat metastatic melanoma in 2011, 5 more checkpoint blockade therapies have emerged, all of which target the PD-1/PD-L1 axis and are used for treating several tumor types." (PMID 35145371, 2022). "In metastatic melanoma patients and mouse models, SCFAs (butyrate and propionate) limit the antitumor effects of CTLA-4 inhibitors via inducing CTLA-4 blocking resistance and a high proportion of Tregs." (PMID 35355998, 2022). "Ipilimumab was approved in the United States and Europe in 2011 for the treatment of unresectable or metastatic melanoma, making CTLA-4 the first immune checkpoint to be targeted in cancer immunotherapy." (PMID 35954362, 2022). "In metastatic melanoma, combined anti-CTLA-4 (ipilimumab) and RT resulted in favorable response rates and survival relative to prior reports of ipilimumab alone." (PMID 35440655, 2022). "Ipilimumab is a human anti-CTLA4 antibody already approved for the treatment of metastatic melanoma and given by IV injection." (PMID 36134952, 2022). "In metastatic melanoma, combination CTLA-4 and PD-1 inhibition led to a five-year overall survival rate of more than 50%." (PMID 35744922, 2022). "Here, we present a case of a 70-year-old male patient with widespread metastatic melanoma who developed rapid onset anasarca and transaminitis after initiation of dual anti-PD-1/CTLA-4 inhibition with nivolumab and ipilimumab." (PMID 35493494, 2022). "Th17 cells can be expanded ex vivo with anti-CTLA-4 from CD4+ T-cells and whole PBMCs isolated from anti-CTLA-4-treated metastatic melanoma patients." (PMID 35326731, 2022). "In subjects with metastatic malignant melanoma of the CNS, immunotherapy based on checkpoint inhibition (anti-programmed death-1 or anti-CTLA-4) has shown marked activity in recent years." (PMID 35060532, 2022). "Immunotherapy of melanoma preferably consists of the PD-1 blockers nivolumab and pembrolizumab and the CTLA-4 antibody ipilimumab as monotherapies or in combination, the latter of which has advantages for patients with metastatic melanoma." (PMID 35406541, 2022). "Another study developed a new algorithm dubbed IMPRES (IMmuno-PREdictive Score), which can predict response to anti-PD-1 and/or anti-CTLA-4 immune-checkpoint inhibitors in metastatic melanoma." (PMID 35641998, 2022). "The results were presented at ASCO 2021, and relatlimab was approved by the FDA as treatment for unresectable or metastatic melanoma on March 18, 2022, and were included in the PD-1/PD-L1 and anti-CTLA-4 antibody immunotherapy lineup." (PMID 36091105, 2022). "The US Food and Drug Administration (FDA)-approved treatments for metastatic melanoma, including immune checkpoint blocking antibodies (such as anti-CTLA-4 and anti-PD-1), have an effect on reducing population mortality." (PMID 36601121, 2022). "Nevertheless, the feasibility of a similar approach has been demonstrated in metastatic melanoma patients by blockade of CTLA-4 in combination with moDCs." (PMID 34821951, 2022). "The first cancer immunotherapy drug approved by the Food and Drug Administration (FDA) in 2011 was ipilimumab, a cytotoxic T-lymphocyte antigen 4 (CTLA4)-blocking monoclonal antibody (mAb) for metastatic melanoma." (PMID 35910213, 2022). "In another study in mice, short chain fatty acids (SCFAs) produced by gut microbiota inhibited CD80/CD86 upregulation on dendritic cells induced by anti-CTLA-4 treatment, limiting the efficacy of anti-CTLA-4 in mice with metastatic melanoma." (PMID 36358736, 2022). "In metastatic melanoma patients, four cycles of the CTLA-4 antibody ipilimumab demonstrated a durable response." (PMID 36443704, 2022).
metastatic melanoma (continued). "The use of the immunotherapy combination blockade of anti-PD1 and anti CTLA-4 (Ipilimumab+Nivolumab) has shown the best results in metastatic Melanoma patients to date, but at the cost of about 60% G3-4 immune related adverse events." (PMID 36419899, 2022). "Anti-CTLA-4 antibodies, including ipilimumab and tremelimumab, can improve the prognosis of metastatic melanoma and boost anti-tumor responses in BC." (PMID 36084948, 2022). "In 2010, ipilimumab, a CTLA-4-blocking human monoclonal antibody, enhanced overall survival in patients with metastatic melanoma." (PMID 35954362, 2022). "The anti-CTLA-4 drugs (including Ipilimumab) and anti-PD-1 drugs (including Nivolumab and Pembrolizumab) have therapeutic effects in advanced metastatic melanoma and are used as adjuvant therapy after surgery." (PMID 36601121, 2022). "Analysis of the fecal microbiota of metastatic melanoma patients receiving ipilimumab (anti-CTLA4 Abs) revealed that the enriched Faecalibacterium were associated with a longer survival, but also an increased occurrence of ipilimumab-induced colitis." (PMID 36429112, 2022). "Ipilimumab, a CTLA-4 checkpoint inhibitor, significantly improves survival in patients with metastatic melanoma." (PMID 35936003, 2022). "In this study, we searched and analyzed four available human datasets with RNA-seq data and clinical information from metastatic melanoma patients treated with anti-PD-1, anti-PD-L1, anti-CTLA-4 monotherapy, or a combination of any two." (PMID 36671443, 2022). "In our study, the tumor response assessed at 3 months using imPERCIST 5 and PERCIST5 PET/CT criteria in patients with advanced or metastatic melanoma treated with first-line anti-PD1 +/−anti CTLA4 combination is a predictor of OS." (PMID 35804963, 2022). "Ipilimumab, a monoclonal antibody that recognizes cytotoxic T-lymphocyte associated protein 4 (CTLA-4), was the first immune checkpoint inhibitor approved by the FDA to treat metastatic melanoma patients." (PMID 35237846, 2022). "CTLA-4 blockade, by ipilimumab, introduced in recent years in the treatment of metastatic melanoma, NSCLC and other cancers, incurs severe adverse events associated with toxicity, as observed by the high levels of TNF-α." (PMID 36355837, 2022). "In a further project, 53 patients with metastatic melanoma were treated with sequential anti-CTLA-4 (ipilimumab) and anti-PD-1 (pembrolizumab) therapy." (PMID 35641998, 2022). "We next asked whether critical immune mechanisms underlying the core features of 7HP349’s effect on CTLA-4 checkpoint blockade antitumor response in our preclinical model were associated with a specific treatment outcome for anti–CTLA-4 therapy in patients with metastatic melanoma." (PMID 35552271, 2022). "Antibodies to CTLA-4 and PD-1/PD-L1 have recently been identified for their role in the treatment of a variety of malignancies, including metastatic melanoma and nivolumab for non-small cell lung cancer (NSCLC)." (PMID 35744922, 2022). "Monoclonal antibodies directed against CTLA4, such as ipilimumab, presented significant clinical benefit for individuals with metastatic melanoma." (PMID 36222286, 2022). "Combined with another published dataset of metastatic melanoma received anti-CTLA-4 (VanAllen15; n = 42), we further validated the prediction accuracy of IRGPI for ICI therapy in two datasets (PUCH and VanAllen15) with AUCs of 0.737 and 0.767, respectively." (PMID 35280982, 2022). "Ipilimumab (trade name: Yervoy), a CTLA-4 inhibitor, was first introduced for the treatment of metastatic melanoma while tremelimumab, another CTLA-4 inhibitor, was initially explored for its efficacy in malignant mesothelioma." (PMID 35559250, 2022). "Differently from what observed with anti-CTLA-4 therapies, blockade of PD-1 has been described to expand specific clones, resulting in a less diverse T-cell populations in metastatic melanoma patients." (PMID 36550555, 2022).